ZNF764 (zinc finger protein 764)
Description:
Zinc finger protein that functions as a cofactor for steroid hormone receptors, such as NR3C1/GR. Directs NR3C1/GR transcriptional activity toward specific biologic pathways by changing NR3C1/GR binding and transcriptional activity on the glucocorticoid-responsive genes.
Synonyms: MGC13138
Tractability: No criterion of Open Targets' tractability assessment is met for any kind of drug.
Gene: Protein-coding gene on chromosome 16 (30,553,764 to 30,558,374, reverse strand). Ensembl gene ENSG00000169951.
Subcellular location: Nucleus
Subcellular location (Human Protein Atlas): Cytosol
Pathways (Reactome):
Gene expression (Transcription): Generic Transcription Pathway
Gene Ontology:
Molecular function: protein binding; transcription coregulator activity; DNA-binding transcription factor activity, RNA polymerase II-specific; RNA polymerase II transcription regulatory region sequence-specific DNA binding
Biological process: cellular response to glucocorticoid stimulus; regulation of transcription by RNA polymerase II; regulation of DNA-templated transcription
Cellular component: nucleus
Genetic constraint (gnomAD): Loss-of-function variants: 10 observed, 12.66 expected, observed/expected ratio (o/e) 0.79, 90% interval 0.49 to 1.34. The synonymous counts are far from expectation, so gnomAD's model fits this gene poorly and the ratio says little. Missense variants: 647 observed, 536.99 expected, observed/expected ratio (o/e) 1.2, 90% interval 1.13 to 1.29. Synonymous variants: 313 observed, 232.73 expected, observed/expected ratio (o/e) 1.34, 90% interval 1.23 to 1.48.
Homologues: Orthologues: chimpanzee ZNF764 (99% identical), rat Zfp764l1 (66% identical), mouse Zfp764l1 (65% identical), rat Zfp764 (65% identical), mouse Zfp764 (60% identical), zebrafish si:dkey-89b17.4 (23% identical), zebrafish znf646 (23% identical), Drosophila melanogaster CG18011 (18% identical), Drosophila melanogaster az2 (17% identical), Drosophila melanogaster CG1602 (16% identical), zebrafish znf576.1 (15% identical), Drosophila melanogaster CG2129 (15% identical), and 8 more. Paralogues in human: ZNF747 (68% identical), ZNF785 (44% identical), ZNF689 (43% identical), ZNF688 (33% identical), ZFP92 (30% identical), ZNF420 (30% identical), ZNF160 (30% identical), ZBTB24 (29% identical), ZNF48 (29% identical), ZNF91 (29% identical), ZNF574 (28% identical), ZNF594 (28% identical), and 24 more.